ALK (ALK receptor tyrosine kinase)
Diseases named in the same sentence as ALK in open-access papers (continued):
Sharing a sentence is not in itself a finding about the gene and the disease.
acute myeloid leukemia (19 papers, 2012 to 2025). Acute myeloid leukemia (AML) is a group of neoplasms arising from precursor cells committed to the myeloid cell-line differentiation. "More recently, oncogenic ALK fusions have been identified in a small subset of patients with acute myeloid leukemia (AML) and other myeloid-lineage hematologic malignancies." (PMID 37509482, 2023). "According to a study, gilteritinib, a TKI approved for the treatment of acute myeloid leukemia (AML) that has relapsed or become resistant to treatment, suppresses both single ALK-TKI-resistant mutants and compound mutants with the mutation I1171N both in vitro and in vivo." (PMID 36499382, 2022). "CM14 overcomes ALK inhibitor resistance in ALCL and is also active in T-cell Acute Lymphoblastic Leukemia and Acute Myeloid Leukemia." (PMID 40073758, 2025).
fibrosarcoma (19 papers, 2019 to 2026). A malignant mesenchymal fibroblastic neoplasm affecting the soft tissue and bone. "Such treatments were considered in 15 of the 23 NSCLC dossiers for the following mutations: anaplastic lymphoma kinase (ALK), rapidly accelerated fibrosarcoma-isoform B (BRAF), epidermal growth factor receptor (EGFR) and the C-ros oncogene 1 (ROS1)." (PMID 32236766, 2020). "ALK rearrangements are rarely documented in superficial soft tissue neoplasms exhibiting an infantile fibrosarcoma-like spindle cell tumor (IFS) pattern or stromal, resembling Neurotrophic Tyrosine Kinase Receptor(NTRK)rearranged spindle cell tumors." (PMID 40510160, 2025). "Recently, new entities have been described based on molecular anomalies, such as the NTRK-rearranged spindle cell neoplasms, the EWSR1-SMAD3-rearranged fibroblastic tumor, or the ALK-rearranged infantile fibrosarcoma-like tumor." (PMID 35565289, 2022). "These include activating mutations in epidermal growth factor receptor (EGFR) and B-rapidly growing fibrosarcoma (BRAF) or anaplastic lymphoma kinase (ALK) fusions and c-ros oncogene 1(ROS1) receptor tyrosine kinase fusions." (PMID 34572789, 2021). "However, their efficacy in ALK-driven infantile fibrosarcoma of the hand has been documented rarely." (PMID 41439260, 2026). "Although ETV6-NTRK3 is a genetic hallmark of infantile fibrosarcoma, it has also been reported in ALK-negative IMTs." (PMID 32957984, 2020). "Overall, gene fusion is a common genomic structural variation in PTC, targeting, besides RET, several other kinases, such as NTRK1, NTRK3 (N Tropomyosin Receptor Kinase), ALK (Anaplastic Lymphoma Kinase), HGFR (Hepatocyte Growth Factor Receptor), and BRAF (B Rapidly Accelerated Fibrosarcoma)." (PMID 32326537, 2020). "Although infantile fibrosarcomas with NTRK gene fusions are well documented, there is less information on the management of tumors that have similar morphology (i.e., “infantile fibrosarcoma-like” [IFS-like] neoplasms) but harbor anaplastic lymphoma kinase (ALK) fusions." (PMID 41439260, 2026). "Moreover, it has been shown that JUNB is induced by ALK-NPM, participating the mTOR pathway and is required for cell cycle re-entry, after quiescence, and it cooperates with c-jun for the development of fibrosarcoma." (PMID 31370904, 2019).
Hodgkins lymphoma (18 papers, 2006 to 2025). A heterogeneous group of malignant lymphoid neoplasms of B-cell origin characterized histologically by the presence of Hodgkin and Reed-Sternberg (HRS) cells in the vast majority of cases. "On 2011, it was approved by the FDA for the treatment of Hodgkin lymphoma (HL) patients, but it may also be adopted in cases of ALK-positive large B-cell lymphoma (LBCL) and Primary Effusion LBCL." (PMID 31214498, 2019). "Of the 3 case reports using BV in patients requiring hemodialysis, 2 detail management of classical Hodgkin lymphoma, whereas the third discusses using BV in a case of ALK negative systemic ALCL." (PMID 40740736, 2025). "Jaffe have suggested that HL-like ALK negative ALCL should be diagnosed only when tumor cell morphology closely resemble Hodgkin’s lymphoma but immunohistochemical study show characteristics of ALCL (positive staining for CD30, EMA, CD3 but negative for EBV and B-cell markers)." (PMID 27612448, 2016). "The nodular lymphocyte-predominant subtype of Hodgkin lymphoma shares an IHC profile with T-cell/histiocyte-rich DLBCL and ALCL, ALK-negative, and similar clinicopathologic features." (PMID 37046526, 2023). "As ALCLs are consistently negative for EBV according to the WHO, case 3 may not fit into the category of ALK-negative ALCL with current criteria and may represent rare intracerebral Hodgkin lymphoma." (PMID 34791573, 2022).
leiomyosarcoma (18 papers, 2016 to 2025). An uncommon, aggressive malignant smooth muscle neoplasm, usually occurring in post-menopausal women. "The same mutation of the ALK gene (C928fs) was demonstrated in a sample of Ewing’s sarcoma and leiomyosarcoma." (PMID 29541442, 2018). "We also reported TNS1-ALK fusions in two uterine sarcomas, and a case report described a patient with leiomyosarcoma benefiting from matched therapy with the ALK inhibitor brigatinib after failing multiple lines of chemotherapy." (PMID 40711866, 2025). "Two of four (50%) eligible ALK fusion–positive patients responded to treatment (one with leiomyosarcoma and the other with CRC)." (PMID 38938274, 2024). "Leiomyosarcomas and sarcomatoid carcinomas usually lack ALK expression, especially when necrosis is present." (PMID 35308527, 2022). "Besides IMF, ALK fusions have also been detected in a small subset (<2–5%) of leiomyosarcoma involving a range of different fusion partners such as KANK2 and ACTG2, two proteins highly expressed in smooth muscle, and STK32B, IGFBP5, and TNS1." (PMID 38611033, 2024). "Therefore, we conclude that the leiomyosarcoma had unambiguously developed from one of the leiomyomas as a result of secondary genetic alterations i.e. a rearrangement of ALK and a del(14q)." (PMID 29963223, 2018). "An emerging fusion partner of ALK, TNS1, was recently described in uterine leiomyosarcomas; we observed this fusion in 16 cases (12 cases in uterine and non-uterine LMS) in the current cohort." (PMID 35705558, 2022). "Leiomyosarcomas may have a prominent inflammatory cell infiltrate but show conventional leiomyosarcoma morphology and are diffusely positive for SMA and negative for ALK." (PMID 32867125, 2020).
primary effusion lymphoma (17 papers, 2009 to 2025). A large B-cell lymphoma located in the body cavities, characterized by pleural, peritoneal, and pericardial fluid lymphomatous effusions and that is always associated with human herpes virus-8 (HHV-8). "The most common types of these include plasmablastic lymphoma, primary effusion lymphoma, large B-cell lymphoma arising from HHV8-associated multicentric Castleman’s disease, and ALK+ large B cell lymphoma." (PMID 28191314, 2017). "Differential diagnosis of ALK-DLBCL should include lymphoblastic lymphoma, anaplastic variants of DLBCL, plasmablastic lymphoma (PBL), primary effusion lymphoma (PEL), solid variants of PEL and plasmablastic myeloma." (PMID 19250532, 2009). "Different subtypes can be identified via an additional IHC panel consisting of Cyclin D1, kappa/lambda, CD30, CD138, EBER-ISH, ALK, and HHV8 (primary effusion lymphoma)." (PMID 33216822, 2020). "From these observations, the possibility that the current case was EBV-positive LBCL with plasmacytoid differentiation, primary effusion lymphoma (PEL), plasmablastoma (PBL), ALK+ LBCL, or HHV8+ DLBCL, NOS was dismissed." (PMID 36581860, 2022).
hepatocellular carcinoma (16 papers, 2015 to 2025). A malignant tumor that arises from hepatocytes. "Similar reports have been limited to the efficacy of ICL combined with bevacizumab in patients with advanced cholangiocarcinoma, hepatocellular carcinoma, and cervical carcinoma, mostly focusing on the inhibition of PD‐1 expression, ALK positivity, and EGFR mutation, and so forth." (PMID 40488279, 2025). "Ceritinib has demonstrated antitumor activity in hepatocellular carcinoma cells by inhibiting the ALK and insulin-like growth factor 1 receptor (IGF1R) signaling pathways." (PMID 38399413, 2024). "ALK expression without any rearrangement or amplifications of the ALK has, been reported in hepatocellular carcinoma associated with poor prognosis and occurrence of micrometastases." (PMID 28359267, 2017). "A high ALK expression without an activating mutation or fusion of the ALK gene is also observed in Hepatocellular carcinoma (HCC) and it is correlated to presence of Hepatitis C Virus infection and further to earlier development of metastasis and lower survival." (PMID 34029351, 2021). "ALK-CNG was further identified in the 13 % of patients affected by hepatocellular carcinoma, negative for serum hepatitis B virus DNA, with a significant correlation among ALK-CNG (≥4 copies versus < 4 copies), 3-year PFS rate (27 % versus 42 %) and 3-year OS rate (18 % versus 47 %)." (PMID 27561692, 2016). "Further, atezolizumab plus bevacizumab is the standard of care for patients with unresectable hepatocellular carcinoma, and atezolizumab plus bevacizumab in combination with chemotherapy is approved for patients with metastatic non-squamous NSCLC and no EGFR or ALK alterations." (PMID 34940094, 2021).
anaplastic thyroid carcinoma (15 papers, 2011 to 2025). "In anaplastic thyroid carcinoma, two ALK point mutations, C3592T and G3602A, were identified in the tyrosine kinase domain, promoting cell proliferation and invasion by activating signaling pathways." (PMID 40636700, 2025). "ALK-L1198F and ALK-G1201E mutations were originally identified in anaplastic thyroid cancer (ATC) and characterized as constitutively activating mutations." (PMID 28030793, 2017). "Recently ALK point mutations were reported in anaplastic thyroid cancer (ATC), at residues ALK-L1198F and ALK-G1201E." (PMID 28030793, 2017). "We have recently reported a case of an ALK gene rearrangement detected by FISH both in an anaplastic thyroid carcinoma (ATC) with PTC component and in its lung metastases." (PMID 24475247, 2014). "Crizotinib is an inhibitor of anaplastic lymphoma kinase (ALK) andc-MET.Recently, rearrangements involving theALKgene were discovered in rare, poorly differentiated, and anaplastic thyroid cancers and, more frequently, in radiation-induced DTC." (PMID 28225999, 2017).
esophageal squamous cell carcinoma (15 papers, 2012 to 2024). Esophageal squamous cell carcinoma (ESCC) is a type of esophageal carcinoma (EC) that can affect any part of the esophagus, but is usually located in the upper or middle third. "This study investigates the role of three specific proteins—FGF8, ALK, and EML4—in predicting the prognosis of patients with esophageal squamous cell carcinoma (ESCC), a common type of esophageal cancer." (PMID 39518064, 2024). "The aim of this study was to examine the prognostic role of FGF8, ALK, and EML4 in esophageal squamous cell carcinoma (ESCC)." (PMID 39518064, 2024).
Ewing sarcoma (15 papers, 2014 to 2025). A small round cell tumor that lacks morphologic, immunohistochemical, and electron microscopic evidence of neuroectodermal differentiation. "Two separate studies have described the presence of ALK mutations in Ewing’s sarcoma and have hypothesized that this mutation may be targetable with Crizotinib." (PMID 29541442, 2018).
neuroendocrine tumors (15 papers, 2014 to 2025). "Drug development of immunotherapy targeting NSCLC with a driver mutation involving ALK and advanced neuroendocrine tumors (NETs) including pulmonary LCNEC are currently ongoing." (PMID 33352665, 2020). "The majority of neuroendocrine neoplasms (NENs) with ALK fusion are associated with metastasis, a higher grade, and a poorer prognosis, suggesting that pulmonary NECs with ALK fusion may indicate worse outcomes." (PMID 37373998, 2023). "Moreover, our study shows that ALK IHC alone is an insufficient diagnostic method to assess the ALK status in neuroendocrine tumors of the lung, requiring integration of FISH and NGS into the diagnostic algorithm." (PMID 35756632, 2022). "Our study shows that, unlike in NSCLC, IHC is an insufficient tool for the diagnosis of ALK rearrangement in neuroendocrine tumors of the lung due to the high prevalence of false-positive cases and low specificity." (PMID 35756632, 2022). "Based on the 3 illustrated ALK-rearranged index cases out of our clinical routine, we aimed to analyze the prevalence of ALK rearrangements in a retrospective cohort of 436 neuroendocrine tumors of the lung, including LCNEC, SCLC, TCs, and ACs." (PMID 35756632, 2022). "Contrarily to NSCLC, the detection of ALK rearrangements in neuroendocrine tumors of the lung is challenging, since ALK IHC can lead to false-positive results and therefore needs confirmation by FISH or NGS." (PMID 35756632, 2022). "Clinical characteristics and therapeutic effect of ALK rearrangement in neuroendocrine tumor." (PMID 39667359, 2024). "Similarly, ALK fusions (2.2%) accounted for three of the five fusion-positive cases with neuroendocrine tumors." (PMID 36369474, 2022). "Additionally, ALK fusions also have been rarely found in other neuroendocrine tumors of the lung, such as typical (TCs) and atypical pulmonary carcinoids (ACs), as well as in SCLC." (PMID 35756632, 2022). "In this study, we investigated the prevalence of ALK alterations in a large cohort of neuroendocrine tumors of the lung, including LCNEC, SCLC, TC, and AC (n = 439) by immunohistochemistry (IHC), fluorescence in situ hybridization (FISH), and next-generation sequencing (NGS)." (PMID 35756632, 2022). "These fish developed neuroendocrine tumors resembling human NBL in the interrenal gland, the onset of which could be accelerated by coexpression of anaplastic lymphoma kinase (ALK), which is found to be mutationally activated in approximately 15% of high-risk NBL cases." (PMID 37183823, 2023). "As protein expression of ALK is especially found in neuronal tissue like thalamus, hypothalamus, midbrain and dorsal root ganglia, the question is whether altered ALK present in neuroendocrine tumors of the lung, can act as a target for treatment with ALK inhibitors." (PMID 35677534, 2022). "Given the elevated expression of ALK in a subset of NEPC tumors, we evaluated the gene expression patterns in metastatic neuroendocrine tumor samples from the UW rapid autopsy cohort." (PMID 36337169, 2022). "However, the response to ensartinib in neuroendocrine tumor (NET) with nonclassic ALK rearrangement has rarely been reported." (PMID 39667359, 2024). "Currently, neuroendocrine tumors of the lungs are not screened for ALK rearrangements." (PMID 35756632, 2022). "The conclusion is that ALK-rearrangement may not be of practical importance in LCNEC and that neuroendocrine tumors with ALK-rearrangement may be less responsive to ALK-inhibitors." (PMID 35677534, 2022).
esophageal cancer (14 papers, 2012 to 2024). A primary or metastatic malignant neoplasm involving the esophagus. "Our results are in accordance with previous findings observed in other series of NSCLCs and esophageal cancer reporting negative ALK IHC in ALK-A cases." (PMID 32664698, 2020). "The incidence rate of ALK gene fusion in Chinese CRC patients was 0.44%,but not detectable in gastric and esophageal cancers." (PMID 26678488, 2015).
metastasis (14 papers, 2016 to 2026). The spread or migration of cancer cells from one part of the body (where they first appeared) to another. "Genomic analysis revealed site-specific correlations: MYC mutations with pleural metastasis, NTRK3 with brain metastasis, ALK with adrenal metastasis, and NTRK1 with intrapulmonary metastasis." (PMID 42187573, 2026). "The prevalence of CNS metastasis in patients with specific genomic alterations was the following: ALK (34.9%), RET (32.2%), KRAS (30.2%), EGFR (29.4%), and wild type (28.8%)." (PMID 40423053, 2025). "So, to ensure appropriate management for young female patient harboring ALK fusion, oncologists should be aware of the presence of adnexal or ovarian metastasis particularly." (PMID 27472693, 2016). "We report a case of an anaplastic lymphoma kinase (ALK) fusion‐positive non‐small‐cell lung cancer patient who developed severe hemolytic anemia after starting low‐dose alectinib due to liver failure from diffuse liver metastasis." (PMID 39527462, 2024). "Pathological examination results, ALK, 34βE12, Cam5.2, CK8/18, and lymphatic pleural metastasis were related to PC(C = 18)." (PMID 38691184, 2024). "Presence of synchronous lung metastasis was 12.5 times more prevalent in ALK positive as compared to double negative group (P = 0.007) with an AUC of 0.912 [95% CI: 0.859–0.965]." (PMID 37745691, 2023).
soft tissue tumors (14 papers, 2006 to 2026). "The molecular basis of ALK immunoreactivity observed in diverse fusion-associated soft tissue tumors seems heterogeneous and associates with specific types of fusions (e.g., EWSR1/FUS-TFCP2 and EWSR1 but not MEIS1-NCOA2 and other fusions)." (PMID 34228212, 2022). "ALK rearrangements were most frequently seen in thyroid, colorectal, and soft tissue tumors in this cohort." (PMID 35233056, 2022). "Therefore, GISTs should also be taken into account in the differential diagnosis of ALK-positive soft tissue tumors, especially IMT, because the suggested treatment regimens for IMT and GIST are strikingly different." (PMID 37120571, 2023). "The detection of anaplastic lymphoma kinase (ALK) using immunohistochemistry (IHC) or ALK gene rearrangements using FISH is important for distinguishing IMTs from other soft tissue tumours, which is fundamental for guiding clinical treatment and avoiding associated complications." (PMID 25910080, 2015). "Here, we present two cases of pediatric cutaneous soft tissue tumors with an IFS pattern, in which ALK fusions involving related partner genes were identified." (PMID 40510160, 2025). "Among ALK-related tumors, superficial ALK-rearranged myxoid spindle cell neoplasm (SAMS) is a rare, soft tissue tumor characterized by the immunophenotypical co-expression of CD34 and S100." (PMID 39202049, 2024). "Other RTKs, such as FGFR1 and AXL in the soft tissue tumors, and FGFR1 and ALK in MB-WNT, showed absolute values in the 90th percentile of all tumors, revealing potential therapeutic susceptibilities." (PMID 35978432, 2022). "ALK rearrangements have rarely been reported in S100- and CD34-co-expressing soft tissue neoplasms with lipofibromatosis-like neural tumor (LPFNT) pattern or stromal and perivascular hyalinization, mimicking NTRK-rearranged spindle cell tumors." (PMID 36387173, 2022). "Immunohistochemistry is characteristic of a soft tissue tumor with ALK cytoplasmic positivity in most cases, without being a specific finding for this type of tumor." (PMID 37546157, 2023). "The anaplastic lymphoma kinase (ALK) is detected in the majority of IMTs and is negative in several other soft tissue tumours." (PMID 25910080, 2015).